RNU6-1008P (RNA, U6 small nuclear 1008, pseudogene)
Gene: Small nuclear RNA gene on chromosome 1 (224,305,380 to 224,305,483, forward strand). Ensembl gene ENSG00000206887.
Homologues: Orthologues: chimpanzee U6 (100% identical), macaque U6 (95% identical), rat U6 (86% identical), guinea pig U6 (85% identical), rabbit U6 (84% identical). Paralogues in human: RNU6-41P (88% identical), RNU6-1145P (88% identical), RNU6-1152P (88% identical), RNU6-1159P (88% identical), RNU6-16P (88% identical), RNU6-35P (88% identical), RNU6-393P (88% identical), RNU6-940P (88% identical), RNU6-115P (87% identical), RNU6-12P (87% identical), RNU6-1316P (87% identical), RNU6-13P (87% identical), and 1286 more.